FAP (fibroblast activation protein alpha)
Diseases named in the same sentence as FAP in open-access papers (continued):
Sharing a sentence is not in itself a finding about the gene and the disease.
fibrosis (19 papers, 2010 to 2026). the formation of excess fibrous connective tissue in an organ or tissue in a reparative or reactive process. "Fibrosis is a pathological feature of many diseases, including Duchenne muscular dystrophy where skeletal muscles exhibit high levels of FAP." (PMID 40893164, 2025). "Digital image analysis detected a higher percentage of FAP-positive cells in areas of active fibrosis (p < 0.001) and FAP-positive cells were distributed outside mature fibrosis lesions, clustered in active fibrosis areas or scattered within alveolar septa." (PMID 39188902, 2024). "Visual superimposition of serial Picro Sirius red and FAP-stained sections revealed that FAP-positive cells were rare within highly collagenic mature fibrosis areas." (PMID 39188902, 2024). "It has been shown in the lung murine fibrosis model that the introduction of CAR-T-anti FAPα+ cells 6 weeks after the administration of bleomycin leads to a tendency toward a decrease in αSMA+ myofibroblasts." (PMID 38136590, 2023). "From theeleventh to the thirteenth weeks, while transition from fibrosis to cirrhosiswas under way, the gap in the growth rate of FAP+- andα-SMA+-cells again appeared, in addition to which a slightdecrease in the number of CD45+-cells was recorded." (PMID 37538808, 2023). "While tissue expression of FAP rises, serum concentration declines, inversely proportional to the severity of fibrosis in liver disease and acute coronary syndrome 33,34." (PMID 34335962, 2021). "Across all three settings, key profibrotic markers (FAPα, CD44, S100A9, CTGF and PDGF) were increased under TOX exposure or established fibrosis and were reduced either by RAGE antibody treatment or by clinical improvement." (PMID 41410848, 2025). "OSM augment resulted in the overexpression of FAP and PDPN in OSMR+ stromal cells, which contributed to intestinal fibrosis of IBD patients." (PMID 32332711, 2020). "Another study reported on the antifibrotic CAR T cells designed against fibroblast activation protein (FAP, a marker of activated fibroblasts): Injections of FAP-CAR-mRNA in CD5-targeted LNPs decreased the burden of fibrotic tissue and improved cardiac function in a mouse model of fibrosis." (PMID 37138754, 2023). "Treatment of fibrosis in SSc patients using FAP-tPDT does not have to be restricted only to the skin." (PMID 34884484, 2021).
anemia (18 papers, 2017 to 2025). A reduction in the number of red blood cells, the amount of hemoglobin, and/or the volume of packed red blood cells. "In contrast, a recent study with genetic ablation of FAP in BM-MSC showed severe toxicity with anemia and weight loss." (PMID 35252279, 2022). "Complete ablation of FAP-expressing cells in mice using genetic approaches resulted in body weight loss, anemia, bone marrow hypoplasia and pancreatic toxicity." (PMID 32625204, 2020). "However, FAP is expressed in certain healthy tissues; thus, complete ablation of FAP is impractical and can potentially cause toxicity such as cachexia and anemia." (PMID 39107856, 2024). "Likewise, treatment with the highly active FAP-KIR-CAR resulted in anemia, body weight loss and bone marrow hypoplasia." (PMID 32625204, 2020). "However, since FAP is also expressed in bone marrow stromal cells and osteoblasts, systemic elimination of FAP-positive cells may cause anemia, bone loss, and cachexia." (PMID 40977952, 2025). "Some studies have reported that systemic depletion of FAP+ cells induced bone marrow hypocellularity, anemia, and cachexia in mice." (PMID 38275890, 2024). "Viral vector-based vaccine: Some of the FAP-targeting preclinical studies show extensive lethal bone, cachexia and anemia that would caution against the clinical development of systemic FAP-targeted treatments." (PMID 37035187, 2023). "However, it is important to note that FAP is also expressed in stromal cells of normal tissues, and thus FAP-targeted therapy may induce side effects such as cachexia, anemia, and bone toxicity." (PMID 40890855, 2025). "In particular, there were no cachexia or anemia observed in animals whose FAP expressing cells were depleted." (PMID 35252279, 2022). "Tran and colleagues observed minimal antitumor effect using a CAR with the FAP-5-scFv coupled with mouse CD28, 4-1BB, and CD3ζ intracellular signaling domains, but did observe severe toxicity indicated by significant cachexia and anemia." (PMID 32625204, 2020). "When we conducted formal autopsy studies using two doses of the 4G5 FAP-CAR T cells, we saw reversible mononuclear infiltration of muscle, pancreas, and lung, but with no changes in bone marrow, nor in anemia markers in blood or animal weights compared to the empty vector control." (PMID 37607999, 2023).
atherosclerosis (18 papers, 2015 to 2025). A disease characterized by the build-up of fatty material and calcium deposition in the arterial wall resulting in partial or complete occlusion of the arterial lumen. "Growing evidence that FAP regulates atherosclerosis by modulating the inflammatory response involved in plaque rupture and fibrosis supports the role of FAP in mediating plaque stability and susceptibility to acute coronary events." (PMID 40278373, 2025). "With further development of specific FAP inhibitors, a possible role of FAP as a diagnostic marker and potential target for interventions in different forms of atherosclerosis will be further determined." (PMID 39590809, 2024). "FAP was found to be expressed predominantly on VSMCs in atherosclerosis, deep vein thrombosis, and thoracic aortic aneurysms 6-8." (PMID 40520892, 2025). "Previous studies supported the role of FAP in the fibroinflammatory process of atherosclerosis, with Fap mostly being expressed on the surface of vascular smooth muscle cells in murine atherosclerotic lesions." (PMID 40278373, 2025). "The main goal of this study was to analyze the expression and localization of FAP in different types of atherosclerotic lesions: human atherosclerotic plaques, atherosclerosis postbypass surgery, and after a heart transplant." (PMID 39590809, 2024). "All different types of human atherosclerotic lesioning lesions showed the presence of FAP expression, with different staining patterns in advanced atherosclerotic plaque, vein graft atherosclerosis lesions, and arteriosclerosis after a heart transplant." (PMID 39590809, 2024). "Higher-magnification images are presented to better compare the FAP staining distribution in early atherosclerosis plaques (20× magnification) and the FAP distribution in advanced atherosclerotic lesions (10× and 20×)." (PMID 39590809, 2024). "Using 20× magnifications of the coronary sections, a more diffuse pattern of FAP staining was visualized in the tunica intima with post bypass atherosclerosis and the tunica intima and media in cardiac allopathy after heart transplant." (PMID 39590809, 2024). "The FAP staining was present mostly in the tunica intima in vein graft atherosclerosis, whereas a strongly positive diffuse pattern of F19 staining in the tunica intima and media was present in heart transplant arteriosclerosis." (PMID 39590809, 2024). "On a subcellular level, FAP mediates the development of atherosclerosis, by regulating inflammatory response (involved in rupture of plaques) and fibrotic remodeling (as a mediator of plaque stability)." (PMID 37147478, 2023). "FAP is expressed by myofibroblasts derived from smooth muscle cells in human aortic plaques and is involved in the pathogenesis and progression of atherosclerosis, particularly in inflammatory processes." (PMID 37762974, 2023). "There is increasing evidence that fibroblast activation protein (FAP) orchestrates the development of atherosclerosis, by regulating the tight interaction of inflammatory response and fibrotic alterations." (PMID 37147478, 2023). "Despite its relevant role in the context of atherosclerosis, there is only limited data on the potential usefulness of FAP inhibitor (FAPI)-directed PET as a cardiovascular image biomarker." (PMID 37147478, 2023). "The goal of this study was to evaluate FAP as a target for atherosclerosis imaging with a small molecule." (PMID 25633335, 2015). "Notably, genetic ablation of FAP has been shown to attenuate the development of experimental atherosclerosis, enhance plaque stability, and reduce collagen degradation." (PMID 40520892, 2025).
atherosclerosis (continued). "Immunohistochemical localization of FAP in different types of human atherosclerotic lesions showed the presence of FAP expression with different patterns of staining in advanced atherosclerotic plaque, vein graft atherosclerosis lesions, and arteriosclerosis after a heart transplant." (PMID 39590809, 2024). "In addition, the global deletion of FAPα in apolipoprotein E (ApoE) knockout mice has been shown to accelerate the progression of atherosclerosis." (PMID 38136590, 2023). "The interest in FAP targeted imaging started with the development of radiolabeled FAP inhibitor [125I]MIP-1232 for single-photon emission computed tomography (SPECT) imaging of atherosclerosis." (PMID 35733858, 2022). "However, the marginal expression of the FAP gene that we detected in major arteries is in contrast to a previous study of atherosclerosis, which revealed that FAP was undetectable by immunofluorescence or Western blot in healthy human aortas." (PMID 33082953, 2020). "With all the different types of human atherosclerotic lesions showing FAP-positive staining, the highest expression with a distinct pattern of staining was found in advanced atherosclerotic plaques, vein graft arteriosclerosis lesions, and atherosclerosis after a heart transplant." (PMID 39590809, 2024). "Studies on systemic FAP concentrations during atherosclerosis-related ischemic events showed that a circulating FAP concentration does not correlate with FAP expression in tissues assessed by molecular imaging during acute ischemic events." (PMID 40278373, 2025). "As FAP is uniquely present in chronic inflammatory lesions and has an important role in ECM turnover, it appears to have characteristics that play a role in atherosclerosis and atherosclerotic plaque rupture." (PMID 39590809, 2024). "Although the biological significance of specific FAP cleavage products is not known, there is increasing evidence that FAP activity plays an important role in modifying collagen matrices, particularly in tumors and atherosclerosis." (PMID 26934296, 2016). "The presence and increased expression of FAP in the progression of human atherosclerotic plaques have been shown in previous studies, although it has not been seen to be expressed in the coronary vessels without atherosclerosis." (PMID 40278373, 2025). "In our study, FAP staining was absent in coronary sections without atherosclerosis and increasingly present with increased plaque size and complexity, suggesting that FAP is a marker of activated myofibroblasts in human native atherosclerosis." (PMID 39590809, 2024). "However, in vivo, using FAPα knockout animals in an atherosclerotic plaque model, where FAPα deletion accelerates atherosclerosis, or an infarction model, no increase in either total or fibrillar collagen or fibronectin was found." (PMID 38136590, 2023). "Targeting FAP by [125I]MIP-1232 may, therefore, be of low relevance for atherosclerosis imaging." (PMID 25633335, 2015). "However, a study on human carotid atherosclerotic plaques showed only a moderately higher level of FAP expression in atherosclerosis plaques than in normal arteries with the binding of a boronic acid-based FAP inhibitor, and this expression was independent of plaque vulnerability." (PMID 39590809, 2024).
breast tumor (18 papers, 2011 to 2025). "Analyzing eight primary human breast tumors identified 8 FAP+ fibroblast populations, following up on previous data emphasizing the importance of FAP." (PMID 38525245, 2024). "Our intent was to use the cre line that expressed in the majority of breast tumor CAFs (as defined by FAP staining)." (PMID 31144616, 2019). "In MMTV-PyMT breast tumors we found that FSP1cre was expressed in the majority of CAFs (75% of FAP+ cells were red)." (PMID 31144616, 2019). "In WT breast tumor organoids embedded within collagen I there was abundant active β1 Integrin present in both CAFs (FAP +ve) and tumor cells (FAP -ve) (quantified in D and E)." (PMID 31144616, 2019). "Very little is known about the FAP+ HO-1+ subset of macrophages, which can be found in both human and murine breast tumours." (PMID 30054470, 2018). "We further show that FAP positive TAFs and SR-A positive TAMs co-localize in the stroma of breast tumors from MMTV-PyMT mice." (PMID 26934296, 2016). "Recently, single-cell analysis of human breast tumours identified a cluster of FAP+ fibroblasts whereby subpopulations enriched in ECM proteins and TGFβ1 signalling were linked with regulation of host immune response via upregulation of PD-1 and CTLA4 expression on Tregs." (PMID 34740105, 2021). "The results showed that MpEV-EPC exhibited the significantly upregulated expression of vWF, SNAIL, VE-Cadherin, FAP, and ALDH (TEC markers found in breast tumors) in comparison to nEV-EPC or the original EPC." (PMID 38515582, 2024). "Recently, a population of CD90+ mesenchymal cells found in human and mouse breast tumours contained subsets of FAP+PDPN+ and FAP+PDPN- cells with tumor growth-promoting properties; however, only the CD90+FAP+PDPN+ subset was immune suppressive." (PMID 34740105, 2021). "We also report that inhibition of β1-integrins abrogates the FAP+ ECM facilitated invasive capabilities of pancreatic and breast tumor cells, suggesting that a cell-matrix β1-integrin engagement is important for this FAP+ matrix-dependent process." (PMID 21668992, 2011). "Thus, tumor promoting ability of fibroblasts did not depend on their tissue source of origin (i.e. breast tumor or reduction mammoplasty), nor did it associate with their extent of αSMA, FSP, FAP, or Caveolin-1 expression." (PMID 21957456, 2011). "Given that αSMA, FSP or FAP expression in vitro could not distinguish fibroblasts isolated from human breast tumor specimens versus fibroblasts isolated from disease-free human breast tissues, we sought to identify other proteins whose expression may be enriched in one tissue source or the other." (PMID 21957456, 2011). "Similar to the previous study, mice bearing a xenografted fibrosarcoma (HT1080-hFAP, high FAP expression, large vasculature) or breast tumor (MDA-MB-231, no FAP expression, neovasculature) were injected with the bispecific liposomes and subsequently imaged." (PMID 33946583, 2021).
head and neck cancer (18 papers, 2014 to 2025). A primary or metastatic malignant neoplasm affecting the head and neck. "In head and neck cancers (HNCs), fibroblast activation protein (FAP) is expressed by cancer-associated fibroblasts (CAFs) in the tumor microenvironment." (PMID 35771317, 2022). "Cancer-associated fibroblasts (CAFs) expressing fibroblast activation protein (FAP) have been associated with the aggressive nature of head and neck cancers (HNCs)." (PMID 32447444, 2020). "Fibroblast activation protein (FAP) represents an emerging therapeutic target in head and neck cancers, with FAP-targeted radioligand therapy demonstrating preliminary activity in heavily pretreated populations." (PMID 41515542, 2025). "Further database analysis correlating FAP gene expression with the prognosis of head and neck carcinoma patients revealed that higher expression of FAP was associated with poorer prognosis." (PMID 39891284, 2025). "Targeting CAFs through FAP has shown anti-tumor efficacy in preclinical head and neck cancer models, and a number of FAP-targeting clinical trials in solid tumors are currently ongoing." (PMID 36575316, 2023). "In head and neck cancer, FAP+ CAFs inhibited CD8+ T cell proliferation and promoted regulatory T cell (Treg) recruitment by secreting TGF-β and IL-6." (PMID 37480115, 2023). "By secreting TGF and IL6, -SMA+ FAP+ CAFs in head and neck cancer suppress the growth of CD8+ T cells and increase the recruitment of CD4+ CD25+ T cells." (PMID 36465405, 2022). "On the other hand, pre-clinical mouse models with head and neck cancer show that absence of FAP positive CAF surprisingly did not affect tumour progression or sensitise tumours to combination cisplatin and anti-PD1 treatment." (PMID 40741380, 2025). "The analysis of a single-cell sequencing dataset representing head and neck cancer clearly showed the expression variation between different cell types, with a significantly increased expression of CXCR4 in T cells and of FAP in fibroblasts, as expected." (PMID 36672341, 2023). "Murine anti-FAP antibody F19 showed a significant tumor-inhibitory effect in xenograft models of lung, pancreas, and head and neck cancers with no obvious signs of toxicity." (PMID 31106200, 2019). "Additionally, in head and neck cancer, evidence of diagnostic and therapeutic potential of FAPI ligands could be proven, although no histopathological DSR correlate or FAP IHC has been evaluated in upfront diagnostics." (PMID 37614665, 2023).